MYC (MYC proto-oncogene, bHLH transcription factor)
Diseases named in the same sentence as MYC in open-access papers (continued):
Sharing a sentence is not in itself a finding about the gene and the disease.
tumor (continued). "Further experiments with more ER + PDXs will need to address whether MYC activity also determines the metastatic potential of the tumor cells and whether the observed differences in response to P4 stimulation also translate into different sensitivities to PR signaling abrogation." (PMID 35668111, 2022). "In addition, recently, S. Greg Call and colleagues showed that the nuclear receptor encoding gene NR4A1, known as a tumor suppressor in AML, as well as a drug inducing its expression, named Dihydroergotamine, are able to inactivate an oncogenic SE associated with MYC expression." (PMID 35053311, 2022). "While this experiment provides robust quantitative insight into the oncogenic potential of MYC S146L, further evidence using mouse models of tumor formation may additionally support our findings and give insight in a system more recapitulative of human disease." (PMID 36018850, 2022). "Moreover, MYC controls proliferation, angiogenesis, and mRNA processing in tumor development." (PMID 36068335, 2022). "Moreover, we propose that therapeutics that reactivate MHC-I expression and enhance anti-tumor immune cell infiltration in MYC-high tumors may improve the efficacy of immune checkpoint inhibitor therapies like anti-PD-1 and anti-PD-L1." (PMID 35760778, 2022). "Importantly, each of these six was among the high-MYC-expressing tumor population in our study." (PMID 36139061, 2022). "Furthermore, MYC migration and overexpression may lead to increased aggressiveness of related tumours." (PMID 35222533, 2022). "This phenomenon may form the basis of potential anticancer therapies in MYC-dependent tumours." (PMID 35276890, 2022). "Hence, we next treated these tumor spheres with a pharmacologic MYC inhibitor." (PMID 34951143, 2022). "Interestingly, the genetic inhibition of tumor-preferred oncogene MYC relieves the tumor burden." (PMID 33692331, 2021). "Subsequent studies showed that loss of the tumor suppressors APC and HIPPO can also induce this “superfit” status, although these effects may reflect the ability of these alterations to drive the downstream activation of MYC." (PMID 33861719, 2021). "Although the development of similar directly acting MYC inhibitors has yet to have an impact in the clinic, the BETi that exert much of their activity by downregulation of MYC provide the most promising approach to date to tackle this critical second arm driving many tumours." (PMID 33799592, 2021). "Hence, uncovering this WDR5-N-Myc relationship could be useful for developing new therapies against MYC-driven tumours." (PMID 34884690, 2021). "However, immortalization of MSCs with a proto-oncogene such as MYC may alter the safety profile of the MSCs and their secretion and confer tumorigenic or tumor promoting activities on the cells or their secretion." (PMID 33918628, 2021). "The in vitro regulatory effects of MYC on the enzymes of proline synthesis was corroborated by high levels of these enzymes in a variety of clinical cancers, and knockdown of proline synthesis markedly inhibited the growth and progression of cultured tumor cells." (PMID 34825974, 2021). "The overexpression of c-MYC may account for the radioresistance of some tumor cell types." (PMID 34063424, 2021).
tumor (continued). "It is tempting to speculate that the transfer of oncogenic kinases via EVs operated by MYC mutant cells could contribute to the aggressive behaviour of the overall tumour mass by promoting the metabolic activity of cancer or stromal cells that do not carry oncogenic mutations." (PMID 34847775, 2021). "Moreover, silencing of c-MYC was reported to increase tumor sensitivity to chemotherapy." (PMID 34803511, 2021). "As 3D-conformation has been shown to influence gene expression and regulation in tumor cells, investigating MYC, HIF1A, VHL and PHD gene expression and relevant miRNAs levels could provide insights into the significance of HIF1-α levels in SK-LMS-1 jumbo spheroids." (PMID 34439199, 2021). "In addition, MYC and G2M checkpoints are classic tumor-promoting signaling pathways." (PMID 34434284, 2021). "Interestingly, MYC has been shown to regulate the anti-tumor immune response in murine models of T cell acute lymphoblastic leukemia (ALL) and liver cancer by inducing the expression of CD47 and/or PD-L1 immune checkpoint molecules and recruiting TAMs, while excluding T cells among other mechanisms." (PMID 33842331, 2021). "Notably, linc00485 was associated with the tumour-node-metastasis (TNM) stage in this cancer, and linc00485 overexpression increased the proliferation, migration, and invasiveness of lung cancer cells by directly sequestering miR-298, which targeted MYC." (PMID 34445233, 2021). "Moreover, the biosynthesis of serine and glycine affects cellular antioxidative capability and also promotes tumor growth; The c-MYC oncogene activates the expression of glutaminase (GLS1/GLS2) and glutamine metabolism in cancer cells, and glutamine can be converted to glutamate even in hypoxia." (PMID 33849550, 2021). "The observation that heightened sensitivity to apoptosis caused by ectopic MYC expression is observed in premalignant cells, but not after malignant transformation provides evidence that tumour cells do acquire specific mechanisms to blunt the pro-apoptotic effects of MYC deregulation." (PMID 33799592, 2021). "However, it is possible that MYC transformation may confer tumor-promoting activity on the exosomes." (PMID 33918628, 2021). "Moreover, this cluster tumor is associated with amplified TERC, TERT, MYC, CCND1, and BCL2L1." (PMID 34815793, 2021). "Therefore, miRNA expression profiles induced by MYC could play an important role in tumor progression." (PMID 34930894, 2021). "To determine whether a deterministic approach can account for gross changes in tumor burden before and after oncogene inactivation, we adapted the general 3-compartment model to study the doxycycline-mediated inactivation of MYC using Tet-regulated transgenic T-ALL3." (PMID 33446671, 2021). "This could be explained by a proportion of transformed B cells depending fully on the MYC-oncogenic program and exponential tumor growth in Eμ-Myc animals, which could mask biologically relevant effects of additional CXCR4 hyperactivation as used in our experimental approach." (PMID 34363012, 2021). "Furthermore, dormant cells upon MYC reactivation again reverted to tumor state." (PMID 33958005, 2021). "However, DMBA-induced elevated expression of MYC and MYCN oncoproteins cause an increase of miR-9 expression in tumor cells, which (this time via a positive feedback mechanism, supporting oncogenes)–through the amplification of E-cadherin–induces further increase of C-MYC expression." (PMID 33539381, 2021). "Indeed, when c-MYC activation/overexpression was coupled to overexpression of the anti-apoptotic gene Mcl-1, the pro-apoptotic function of TGFβ1 was bypassed, ultimately resulting in tumor formation." (PMID 33608500, 2021). "However, how MYC drives tumorigenesis in a subset of Group 3 tumor cells remains to be defined." (PMID 33816256, 2021).
tumor (continued). "However, MYC oncogene addiction involves both tumor-intrinsic pathways including proliferation arrest, apoptosis, and differentiation, as well as tumor-extrinsic pathways including the shut-down of angiogenesis and cellular senescence, which are processes mediated by the host immune system." (PMID 33446671, 2021). "This study uncovered remarkable activities for the three MYC-dependent lncRNAs, lncMB1, lncMB2 and lncMB3, in a G3 MB landscape, and identified their target gene(s), which will further future studies aimed at building novel regulative circuits that are altered in this aggressive pediatric tumor." (PMID 34359754, 2021). "Together these in vitro and in vivo results indicated that loss of AR activity in response to androgen deprivation at AR/MYC co-regulated genes is buffered by an increase in MYC, along with an increase in expression of MYC-unique genes that may further enhance tumor growth." (PMID 34911936, 2021). "In addition, tumor oncogenes or tumor suppressors control cell migration and viability, and may be affected by hypoxia (MYC and HIF) with a role in GBM angiogenesis." (PMID 34646821, 2021). "Similarly, transgenic mouse models have shown that MYC overexpression results in increased tumourigenesis, whilst deletion or reduction in MYC levels, or its inhibition following expression of an engineered dominant negative mutant, can eliminate tumour development in certain models." (PMID 33799592, 2021). "Frequently altered across a broad spectrum of malignancies, MYC orchestrates transcriptional programs promoting metabolic re-wiring and ribosome biogenesis, as well as target gene independent transcriptional processes, ultimately facilitating rampant proliferation and tumor progression." (PMID 34236315, 2021). "Therefore, TGFβ regulated tumor microenvironment reprogramming might be the main mechanism whereby TGFβ promotes c-MYC HCC progression." (PMID 33608500, 2021). "It has also been shown that only small parts of a tumor may harbor c-MYC amplification." (PMID 31454863, 2020). "Furthermore, upon MYC activation, there is not only an increase in the number of macrophages infiltrating the tumor but also an immediate exclusion of T, B and NK cells within the tumor microenvironment." (PMID 33081056, 2020). "Activation of the MYC signalling pathway in normal astrocytes exposed to GBM‐EV may be the mechanism by which GBM acquires a phenotype that promotes tumour progression, MYC was enriched in developmental process and protein binding in this study, was consistent with the predictions of this study." (PMID 32696617, 2020). "It was demonstrated that MYC positively regulate check point inhibitor proteins leukocyte surface antigen CD47 and PDL1 via direct binding to their encoding gene promoters suppressing both the innate and the adaptive immune response while favoring tumor growth." (PMID 32927768, 2020). "Comparing MYC DNA methylation between paired tumor–normal prostate tissue samples from the same men, we found lower DNA methylation in the tumor compared to the paired normal samples for all six CpG sites evaluated, suggesting that these may represent somatic alterations in prostate tissue." (PMID 33374332, 2020). "Interestingly, both p38α and MYC are reported to be linked with the remodeling of tumor immune microenvironment, suggesting that CDK7/p38α/MYC pathway may play a prominent role in the tumor immune microenvironment of NSCLC." (PMID 32690037, 2020). "In the human genome, formation of dynamic G4 structures in the promoter regions of several oncogenes, including MYC, has led to the development of novel, small molecules able to specifically bind and stabilize these G4 motifs to block transcription and stimulate anti-tumor activity." (PMID 33066043, 2020). "Moreover, MYC is a master regulator of tumor energy metabolism." (PMID 32690037, 2020).
tumor (continued). "Furthermore, APC (p < 0.0001), ASXL1 (p < 0.0001), DNMT3B (p = 0.001), PARP4 (p = 0.002), MET (p = 0.01), TOP1 (p = 0.01), KDR (p = 0.01), SRC (p = 0.01), PAK1 (p = 0.015), ALK (p = 0.02), and MYC (p = 0.03) alterations were found to be more common in tumor samples from AO mCRC patients." (PMID 33194656, 2020). "However, the dependency of MYC-driven tumours on NADPH production through serine metabolism and one-carbon metabolism implies that inhibition of these pathways could be an effective anticancer strategy for patients affected by these malignancies." (PMID 31819197, 2020). "Several reports have provided experimental evidence of tRF-mediated tumor suppression through inhibition of either translation initiation or general translation, regulation of ribosome biogenesis and modulation of the stability of factors which promote cell proliferation, like c-MYC." (PMID 33092114, 2020). "Because triple-negative breast cancers express elevated levels of MYC, we speculate that future studies developing similar tumor cell lines may help explore this dual targeting strategy in this group of patients, who have limited options for targeted therapies." (PMID 32685002, 2020). "However, under the PVT1 promoter mutational rearrangements found in tumor cells, and even epigenetic inactivation, PVT1 intragenic enhancer elements interact preferentially with MYC promoter, thus boosting the transcription of MYC oncogene and its oncogenic activity of tumor cells." (PMID 32083000, 2020). "Moreover, MYC is widely involved in tumor development and growth." (PMID 32411526, 2020). "Different mechanisms are explaining how immune evasion mediated by MYC could be achieved: (i) processes directly linked to expression patterns in cancer cells, (ii) crosstalk with other transcription factors, and (iii) MYC-driven recruitment of specialized and co-opted tumor-infiltrating cells." (PMID 33081056, 2020). "Given the divergent activity of MYC in skin on stem cell maintenance, epidermal differentiation, and tumorigenesis, we asked whether regulating MYC phosphorylation can affect the activity of MYC on stem cell maintenance or tumor development." (PMID 32895364, 2020). "However, the MYC oncogene is thought to facilitate escape from this anti-tumor immune response." (PMID 33092116, 2020). "In this study, we used FISH to evaluate the c-MYC gene amplification status in the CTC and, accordingly, matched tumor tissues obtained from GC patients to evaluate whether CTC can replace tissue sampling for the determination of the c-MYC status in GC patients." (PMID 31454863, 2020). "Furthermore, upon mitochondrial oxidative stress, the mitochondrial NADPH pool was reported to be maintained by activation of serine metabolism as knockdown of serine hydroxymethyl transferase (SHMT2) decreased cellular NADPH/NADP+ and impaired tumor growth in MYC‐dependent cells." (PMID 33005744, 2020). "Furthermore, MYC is a pivotal player in the metabolic rewiring of cancer cells, the strategy that cancer cells adopt to cope with the energetic and metabolic demands required to support tumor growth and progression." (PMID 32549409, 2020). "Moreover, while the overexpressed non-mutant (often amplified) c-MYC is a powerful reprogramming factor and oncogene, its downregulation in transgenic mice causes tumour regression." (PMID 33228223, 2020). "Selective inhibition of CDK1/2 and the core component BUD31 of restriction enzymes can induce apoptosis of TNBC tumor cells overexpressing MYC, suggesting that TNBC, especially the BL1 and M subtypes, might benefit from CDK1/2 and restriction enzyme inhibitor treatment." (PMID 32517735, 2020). "Additionally, H19 may be a direct transcriptional target of and is induced by MYC in NSCLC tumor tissues." (PMID 32438606, 2020).
tumor (continued). "Moreover, inhibition of HMG-CoA reductase by atorvastatin was accompanied with blockages of both MYC phosphorylation and activation, suppressed tumor initiation and growth in vivo in a transgenic model of MYC-induced HCC as well as in human HCC-derived cell lines." (PMID 32162652, 2020). "Thus, we speculated that CDK7 ablation could prevent the immune escape of tumor cells by suppressing the MYC/PD-L1 axis." (PMID 32690037, 2020). "In addition, the coexpression of lncRNAs and tumorigenesis gene (well-known oncogene MYC and lncRNA Pvt1) is found in various tumors, which suggests that lncRNAs may have an important direct relationship with tumor growth." (PMID 31850199, 2019). "Therefore, a possible explanation for the results obtained in the present study is that CIAPIN1 may be recruited by MYC to maintain the angiogenesis required for tumor progression." (PMID 31645899, 2019). "In addition, we determined whether PGG-induced inhibition of MYC is a universal phenomenon in tumor cells." (PMID 30760754, 2019). "Thus, the presence of the factors inducing phosphorylation of c-MYC on Ser-62 could deactivate the tumor suppressing effect of BIN1." (PMID 31496920, 2019). "More specifically, given that MYC drives the glucose and glutamine metabolism of cancer cells, the use of small molecules, able to inhibit enzymes involved in glycolysis and glutaminolysis, might be effective in slowing down tumor cell proliferation." (PMID 31341534, 2019). "The tumor fraction of our samples might have influenced the c-MYC GCN detection by ddPCR." (PMID 30733532, 2019). "However, a frequent phosphorylation of c-MYC at Ser-62 site could block the BIN1/c-MYC interaction and limits the tumor-suppressive effect of BIN1." (PMID 31496920, 2019). "EBV infection among the study participants may be associated with BL, however, EBER-1 and MYC negative in BL tumours suggest alternative BL pathogenesis or variant." (PMID 32180880, 2019). "Indeed, MYC is well known to regulate ribosome biogenesis and translation through multiple mechanisms, and we previously demonstrated that MYC inactivation leads to shutdown of global protein synthesis resulting in cellular senescence and tumor regression." (PMID 31266538, 2019). "We also assayed how elevated expression of c-MYC in MSC would affect their bone tissue formation ability in vivo and whether it might enforce a potential risk of tumor formation in recipients, to address the concerns about consequent implications for therapeutic compatibility of these cells." (PMID 30836996, 2019). "Interestingly, both the tumor microenvironment and glycosylation have little to do with the replicative immortality of tumor cells, their contribution is mainly based on the indirect regulation of the transcription factor c-MYC and kinase cascades." (PMID 31157165, 2019). "Six genes (including genes encoding ER, PR, HER2 and their transcription factors MYC, FOXA1, MYBL2) were removed from PAM50 (the new panel is named PAM50–6) to exclude their confounding effect on the classifier, as the ground truth was based on tumor classification stratified by ER, PR and HER2." (PMID 31699026, 2019). "However, c-MYC plays not only an important role in cell proliferation, but also is involved in other multiple functions, such as cell differentiation, apoptosis, cell cycle progression, and cellular transformation leading to tumor pathogenesis." (PMID 30836996, 2019). "The most frequently mutated genes across all tumor types included KRAS (30 patients), PIK3CA (16 patients), BRAF (6 patients), EGFR (5 patients), NRAS (4 patients) and ERBB2 (3 patients) whereas CCND1, ERBB2, EGFR and MYC were the genes most frequently subjected to copy number gain." (PMID 29854313, 2018).